HIF1A (hypoxia inducible factor 1 subunit alpha)
Diseases named in the same sentence as HIF1A in open-access papers (continued):
Sharing a sentence is not in itself a finding about the gene and the disease.
tumor (continued). "The impact of lactate on TME tumor evasion has also been observed with HLA-DR- and CD86-high macrophages have a glycolytic phenotype that suppresses the secretion of anti-tumor IL-12 p70 via PKM2/HIF-1α axis." (PMID 40092297, 2025). "After TMZ treatment, the tumor volumes of the HIF1α-and/or HIF2α-knockout groups were significantly (p < 0.01) reduced, and those of the dual-knockout group were lower than those of the single-knockout groups." (PMID 40370575, 2025). "Meanwhile, enhanced HIF-1α expression under hypoxic conditions stimulated tumour cells to secrete VEGF." (PMID 40149700, 2025). "This hypoxic state stabilizes hypoxia-inducible factor 1-alpha (HIF-1α), which promotes the polarization of macrophages toward an M2-like, pro-tumor phenotype." (PMID 40867316, 2025). "HIF-1α is a transcription factor that activates several genes important for tumor cell survival, proliferation and invasion." (PMID 41279823, 2025). "This inhibition leads to the stabilization of hypoxia-inducible factor 1α (HIF1α), promoting tumor growth, although the exact regulatory mechanisms remain incompletely defined." (PMID 41226319, 2025). "While propofol exerts anti-inflammatory and anti-tumor effects, sevoflurane is known to promote immunosuppression and tumor angiogenesis (via HIF-1α), and to impair NK- and T-cell function through oxidative stress pathways." (PMID 41155334, 2025). "Hypoxic conditions have been shown to upregulate exosome secretion from tumor cells, enriching their cargo with pro-angiogenic factors (e.g., VEGF, HIF-1α) that drive tumor progression." (PMID 40429976, 2025). "VEGF is a key factor in the promotion of angiogenesis, and when HIF-1α is activated in tumor cells, the expression of VEGF is increased." (PMID 41160271, 2025). "Regulating the HIF-1α pathway can impede the survival and proliferation of tumor cells and decelerate tumor progression." (PMID 40284275, 2025). "In recent studies, Hif1α deletion in NK cells leads to enrichment of the NF-κB pathway in tumor-infiltrating NK cells and promotes INF-1α expression, which leads to slower tumor growth and improved patient OS." (PMID 40432130, 2025). "In the hypoxic tumor microenvironment, activated HIF-1α inhibits c-Myc by upregulating the transcription of MAX interactor 1, thereby reducing the oxygen demand of tumor cells and shifting metabolism towards glycolysis." (PMID 40424719, 2025). "VEGF, an angiogenic factor regulated by HIF-1α, was assessed to evaluate treatment-induced changes in tumour vascular signalling after MB + FUS + XRT." (PMID 41148833, 2025). "Some reports suggest that in fibroblast cells, the activated HIF1α promotes autophagy, which further can help survive the fibroblast, and increased tumor mass and volume are also observed." (PMID 40444035, 2025). "For example, high levels of HIF-1α expression are associated with poorer survival outcomes; HIF-1α overexpression is also associated with tumor size, tumor stage, lymph node metastasis, and overall survival." (PMID 40887582, 2025). "Unfortunately, abnormal tumor vasculature often leads to high interstitial pressure, hypoxia, and increased HIF-1α expression, enhancing shear stress levels in lymphatics." (PMID 40821116, 2025). "In the control group tumours, the levels of HIF-1α and APCDD1L-AS1 were significantly higher in the intratumoural regions than in the peripheral regions." (PMID 40634956, 2025). "Within solid tumors, vascular irregularities coupled with accelerated tumor proliferation generate localized oxygen deprivation, leading to pronounced HIF-1α expression in affected regions." (PMID 40901943, 2025).
tumor (continued). "The increased lactate levels in the tumor microenvironment can further induce M2 macrophage polarization by affecting HIF-1α, ERK-STAT3 signaling pathways, and G-protein-coupled receptor 132 (GPR132)." (PMID 40704062, 2025). "HIF-1α is a central driver of tumor metabolic reprogramming, orchestrating the shift from mitochondrial oxidative phosphorylation to aerobic glycolysis." (PMID 41155273, 2025). "Cuproptosis inducers combined with immunotherapy reprogram the tumor microenvironment, with HIF-1α mediating resistance to this combination." (PMID 41185600, 2025). "Under hypoxic conditions, HIF-1α orchestrates the transcription of several genes involved in angiogenesis, tumor growth, invasion, and metastasis." (PMID 40746896, 2025). "In parallel, reader proteins, notably IGF2BP family members can stabilize m6A-tagged targets such as MYC and HIF-1α, reinforcing glycolytic reprogramming, hypoxic signaling, and an immunosuppressive tumor microenvironment." (PMID 41515964, 2025). "HIF-1α, a key transcription factor, allows cancer cells to adapt to the hypoxic tumor microenvironment by promoting angiogenesis, metabolic reprogramming, and stress response pathways." (PMID 39860164, 2025). "Hypoxic conditions commonly found in the tumor microenvironment exacerbate these effects by stabilizing HIF-1α, a key regulator of VEGF expression and vascular remodeling." (PMID 40076537, 2025). "Newly formed blood vessels frequently exhibit structural defects, resulting in irregular perfusion and ongoing tumor hypoxia, which in turn stabilizes HIF-1α and promotes tumor progression." (PMID 40136686, 2025). "Increased and stable expression of HIF-1α due to a reduction of the oxygen concentrations is a common feature observed in both pathologic conditions, tumor progression and (auto)inflammation." (PMID 40963621, 2025). "This confirms the theory that in hypoxic conditions, i.e., during tumor growth and development, HIF-1α is released, supporting further growth of the pathological change." (PMID 40429943, 2025). "HIF1α is often up-regulated in CM respect to normal tissues, and in metastasis compared to primary tumor." (PMID 39953610, 2025). "Our findings demonstrate that hypoxia decreases the sensitivity of tumor organoids to chemotherapeutic agents by upregulating SUMOylation, potentially intersecting with HIF-1α-mediated pathways." (PMID 41268439, 2025). "We developed TNBCvax, a multi-antigen, multi-peptide vaccine designed to simultaneously target three key tumor-associated antigens: TOP2A, HIF-1α, and IGF-1R." (PMID 40969744, 2025). "miR-27a-3p appears to be a pivotal factor in the functional duality of TGF-β and its interaction with HIF1A in the hypoxic tumor environment, modulating SMAD partners or TGF-β pathway inhibitors." (PMID 40943648, 2025). "It has been reported that the level of hypoxia-inducible factor-1α (HIF-1α) is significantly elevated in hypoxic tumor cells." (PMID 40438141, 2025). "Physiologically, CSCs often reside in specialized hypoxic niches within the tumor, where HIFs, primarily HIF-1α, mediate metabolic reprogramming to glycolysis and autophagy, supporting CSC maintenance and resistance." (PMID 40869364, 2025). "Hypoxia is a common feature of most tumors, which contributes to epithelial–mesenchymal transition (EMT), drug resistance, and tumor progression through HIF-1α." (PMID 40362444, 2025). "Bevacizumab, a monoclonal antibody against VEGF, has shown efficacy in normalizing tumor vasculature and reducing hypoxia, indirectly inhibiting HIF-1α activity." (PMID 39981236, 2025). "Inhibition of HIF-1α represents a significant approach in cancer treatment, given its involvement in tumor growth, metastasis, and drug resistance." (PMID 40136686, 2025). "This multifunctional platform not only addresses tumor hypoxia but also downregulates multidrug resistance genes and HIF-1α, significantly improving the effectiveness of treatment." (PMID 40453108, 2025).
tumor (continued). "Angiogenesis and dysregulation of the cell cycle are critical steps in tumor development, with HIF-1α playing a significant role in this process." (PMID 40860815, 2025). "HIF-1α staining in tumor cells was present in 39 cases, while 65 cases exhibited HIF-1α positivity in the tumor microenvironment." (PMID 39996842, 2025). "In BCa, hypoxia can also exert a role in promoting tumor progression and cisplatin resistance through the HIF-1α pathway." (PMID 41199784, 2025). "Strikingly, stromal TFE3 suppression showed superior efficacy to tumor‐specific HIF1A silencing, underscoring the dominance of CAF‐mediated resistance." (PMID 40917018, 2025). "For instance, HIF-1α activation enhances tumor cell survival and further suppresses the host's antitumor immune response by impairing immune cell function." (PMID 41190142, 2025). "In hypoxic tumor cells, the upregulation of the hypoxia-inducible factor HIF-1α leads to a subsequent increase in FABP3/7 expression." (PMID 39925801, 2025). "Meanwhile, lactate reinforces tumor glycolysis through HIF-1α- and c-Myc-dependent upregulation of LDHA and MCT4, establishing a positive feedback loop that sustains energy production in PC cells and contributes to immune evasion." (PMID 41458606, 2025). "For instance, the HIF-1α pathway activated in hypoxic environments not only promotes the expression of antioxidant genes but also enhances tumor cell survival by regulating iron distribution." (PMID 40416987, 2025). "In tumor cells, HIF-1α and HIF-2α activation promotes metabolic reprogramming toward glycolysis (the Warburg effect), enhances angiogenesis through VEGF upregulation, and facilitates cell adhesion and invasion via integrins and MMPs." (PMID 41048631, 2025). "In tumor cells, HIF‐1α is often in a state of continuous activation and can remain stable even in an oxygen‐sufficient environment." (PMID 40944417, 2025). "An upfront TACE or TARE can induce tumor hypoxia, leading to the upregulation of hypoxia-inducible factor-1 alpha (HIF-1α) and vascular endothelial growth factor (VEGF), which promotes tumor angiogenesis and progression." (PMID 40361498, 2025). "As a crucial transcription factor in the cellular response to low oxygen levels, HIF‐1α is often activated in tumour environments where oxygen is limited." (PMID 39993964, 2025). "In mouse models, resveratrol (50 μM) inhibited the hypoxic tumor microenvironment induced by PSC fibrosis via HIF-1α, reducing tumor progression." (PMID 40918466, 2025). "Of note, similar observations regarding the role of HIF1A in driving tumor progression have been reported in other cancers." (PMID 39912781, 2025). "Within the hypoxic niche, hypoxia-inducible factor 1-alpha (HIF-1α) is stabilized and initiates transcriptional programs that support tumor invasion and survival." (PMID 40868217, 2025). "During this phase, HIF1A/HIF-1α, which remains stably expressed, enhances tumor-suppressive metabolic reprogramming by activating BNIP3-dependent selective mitophagy, which in turn inhibits glycolysis." (PMID 40851276, 2025). "The oncogenic transcription factors MYC and HIF-1α critically regulate cellular metabolism in cancer by driving metabolic reprogramming that supports tumor growth and survival." (PMID 40707487, 2025). "HIF-1α’s dual role in promoting tumor progression and reshaping the IVM underscores its significance as both a mechanistic driver of cancer pathology and a promising therapeutic target." (PMID 39981236, 2025). "We identified a significant difference in HIF-1α expression in the tumor microenvironment between the mKRAS G12C group and other KRAS mutation groups (p = 0.017)." (PMID 39996842, 2025). "Tumor-associated macrophage EV lncRNAs, such as HISLA, stabilize HIF-1α in cancer cells to enhance glycolysis and chemoresistance via the disruption of PHD2–HIF-1α interactions." (PMID 41511353, 2025).
tumor (continued). "Hypoxia can increase ROS production through HIF-1α activation, affecting both tumor survival and the therapeutic response." (PMID 41551149, 2025). "For example, a hypoxic tumor micro-environment can mediate tumor cell ferroptosis resistance by activating HIF1α and upregulating various anti-ferroptosis molecules such as SLC7A11, GPX4, TFRC and FTH115-17." (PMID 41049011, 2025). "HCC, one of the most hypoxic tumors, has high HIF-1 expression, and inhibition of HIF-1α expression reduces tumor cell proliferation, induces apoptosis, and enhances sensitivity to radiotherapy." (PMID 40076465, 2025). "Bevacizumab, a humanized monoclonal antibody produced from Chinese hamster ovary (CHO) cells targeting VEGF, is a major downstream target of HIF-1α and can reduce angiogenesis and tumor growth." (PMID 39996906, 2025). "Targeting HIF-1α and its downstream pathways offers a promising therapeutic strategy to address tumor growth, metastasis, and drug resistance, thereby enhancing patient outcomes." (PMID 40136686, 2025). "HIF1A (hypoxia-inducible factor 1α) is a key transcription factor that regulates tumor cell metabolism and helps tumor cells survive in hypoxic environments by activating the glycolytic pathway." (PMID 40366858, 2025). "Compared to primary tumors, tumor spheroids showed increased levels of mesenchymal and HIF1α target genes, along with elevated CAPN2 expression." (PMID 40151834, 2025). "Inhibits the PI3K/AKT signaling pathway.Downregulates VEGF and HIF-1α, reducing angiogenesis and improving tumor oxygenation.A radiosensitizer by improving oxygenation." (PMID 41211420, 2025). "In this review, we present ginseng as a HIF-1α inhibitor that can inhibit tumor development in vivo and in vitro cancer models." (PMID 41585262, 2025). "Third, aberrant tumor vasculature creates hypoxic niches that drive lactate accumulation via Warburg effect reprogramming, simultaneously fueling tumor proliferation and polarizing macrophages toward pro-tumoral M2 phenotypes through HIF-1α signaling." (PMID 40313937, 2025). "The high metabolic activity of cancer cells creates hypoxia, which induces HIF-1α, driving tumor angiogenesis and invasion." (PMID 40260236, 2025). "HIF-1α serves as a key regulator of the hypoxic response, influencing tumor progression and impacting ovarian function through mechanisms such as angiogenesis, metabolic dysregulation, oxidative stress, inflammation, and hormonal imbalances." (PMID 40136686, 2025). "Despite these insights into their roles within cancer cells, the functions of HIF1α and HIF2α in the tumor stroma remain largely unexplored." (PMID 40322886, 2025). "The tumor volume of the tumor-bearing mice decreased, and the concentration of multiple molecules in the peripheral blood of the mice, including HIF-1α, TNF-α, VEGF, and MMP-9, was reduced." (PMID 40563539, 2025). "siRNA-basedtherapy against HIF-1α has also been appliedto overcome the resistance to chemophotodynamic therapy, evident inhypoxic tumor environments." (PMID 40184281, 2025). "Existing research has demonstrated that NNK can influence the activity of different components in the tumor microenvironment, such as HIF-1α and β2-AR, thereby promoting the growth of tumor cells." (PMID 40303426, 2025). "TACE has been shown to increase tumour hypoxia, resulting in the upregulation of the hypoxia inducible factor-1α (HIF-1α)." (PMID 41281029, 2025). "The fluorescence revealed the co-expression of PGM2L1 and HIF-1α in the central region of the tumor, which was considered relatively hypoxic regions." (PMID 40185722, 2025). "Hypoxia-inducible factor 1-alpha (HIF-1α) is a key transcription factor that supports tumor growth, metabolism, invasion, and metastasis under hypoxic microenvironments." (PMID 40725100, 2025). "HIF-1α plays a central role in tumor adaptation to hypoxic conditions by regulating key glycolytic enzymes, thus driving metabolic reprogramming essential for metastasis." (PMID 41298345, 2025).
tumor (continued). "Cinnamaldehyde shows promise by targeting the HIF1α/VEGF pathway to inhibit tumor growth, with a reduced side effect profile." (PMID 41459064, 2025). "This overexpression correlates with poor prognosis, radiotherapy resistance, enhanced glycolysis and hypoxia within the tumour microenvironment, as evidenced by positive associations between LDHA expression and markers such as HIF1A and GLUT-1." (PMID 41154605, 2025). "Such a pathway is in agreement with prior findings wherein HIF1A (possibly induced by tumor hypoxia) amplifies ETS1, which in turn promotes metastatic traits." (PMID 40777467, 2025). "Bortezomib facilitates the degradation of HIF-1α, thereby diminishing tumor adaptation to hypoxic conditions and improving the effectiveness of chemotherapy." (PMID 40136686, 2025). "The activation of HIF-1α encourages a metabolic shift towards aerobic glycolysis, allowing tumor cells to proliferate under hypoxic conditions." (PMID 41311849, 2025). "In cervical cancer, elevated lactate levels in tumor tissues promote HIF-1α enrichment at the DCBLD1 promoter region, augmenting DCBLD1 mRNA expression." (PMID 40994548, 2025). "YFJDT treatment significantly reduced tumor weight, HIF1A overexpression promoted the increase in weight, and then additional erastin down‐regulated tumor weight." (PMID 39912781, 2025). "These technologies allow precise identification of immune cell subsets (e.g., distinct Treg or TAM populations), spatial mapping of cytokine/chemokine gradients, and localization of pathway activations (e.g., VEGF, HIF-1α) within tumor niches." (PMID 41020852, 2025). "Hypoxia‐inducible factor 1‐alpha (HIF‐1α) activation has been shown to suppress immunity and promote tumor immune evasion, although the underlying mechanisms require further investigation." (PMID 40437741, 2025). "It has been reported that lactic acid produced by tumor cells is mediated by a hypoxia-inducible factor (HIF-1α) and that lactate-induced arginase 1 expression in macrophages induces M2-like polarization of macrophages in a melanoma murine tumor model." (PMID 40940867, 2025). "The miRNA-7 regulates the process of glycolysis in tumor cells by regulating key pathways, such as hypoxia-inducible factor-1α (HIF-1α), thereby reshaping the acidic TME and inhibiting tumor cell growth." (PMID 39711287, 2025). "We observed that a low WWOX/HIF1A ratio promotes tumour progression by amplifying hypoxia-induced responses, whereas a high ratio contributes to microenvironmental stability and suppresses metastatic features." (PMID 41007296, 2025). "These inhibitors modulate lipid metabolism through LXRα signaling while concurrently targeting tumor glycolysis via HIF1α regulation." (PMID 41583428, 2025). "Under hypoxia, HIF-1α orchestrates metabolic pathways to enhance glutamine-dependent reductive carboxylation, promoting tumor cell growth and proliferation." (PMID 40813760, 2025). "PX-12 inhibits the stabilization of HIF-1α under hypoxic conditions by targeting the thioredoxin system, thereby diminishing tumor resistance to chemotherapy." (PMID 40136686, 2025). "This stabilization of HIF-1α triggers the expression of hypoxia-responsive genes, leading to aberrant angiogenesis, shaping the tumour microenvironment and supporting the survival and maintenance of cancer stem cells." (PMID 40806771, 2025). "Immunohistochemical staining of tumour biopsies manifests the increased HIF-1α protein expression, which positively mediates the expression of VEGF, Stromal cell-derived factor-1 (SDF-1) and stem cell factor and thereby induces the invasion and metastasis." (PMID 40852716, 2025). "In lung tumour lysates MLN0128 monotherapy causes robust inhibition of HIF1α and GLUT1, translating to a significant and maintained reduction in lung tumour FDG avidity and suppression of tumour growth." (PMID 40069402, 2025). "Functionally, ERCC6L promoted LUAD cell stem-like characteristics by regulating tumor glycolysis via the VHL/HIF-1α pathways." (PMID 40691138, 2025).